EGFR (epidermal growth factor receptor)
Diseases named in the same sentence as EGFR in open-access papers (continued):
Sharing a sentence is not in itself a finding about the gene and the disease.
lung cancer (continued). "We also need to distinguish the expression levels of wild-type and mutant EGFR in a certain lung cancer cell or cell line if they are co-expressed." (PMID 40649937, 2025). "Currently, targeted therapies play a crucial role in cancer treatment, with EGFR‐targeted therapy for lung cancer and HER2‐targeted therapy for breast cancer yielding promising results." (PMID 39823250, 2025). "Additionally, in some cases with limited available information on baseline biomarkers in tissue, Follow it® identified mutations that may interfere with the therapy chosen based on tissue testing alone, such as EGFR ctDNA mutations in lung cancer patients with PD-L1 expression." (PMID 41590338, 2025). "By targeting both wild-type and mutant forms of EGFR, asiatic acid emerges as a candidate for further development as a targeted therapeutic agent for lung cancer." (PMID 41154639, 2025). "Mesenchymal-epithelial transition (MET) enhancement often induces resistance to anti-EGFR therapies like erlotinib and gefitinib used in lung cancer treatment." (PMID 40342734, 2025). "Its deficiency increased the expression of antiapoptotic isoform Bcl-xL, leading to tumor progression and worse clinical outcomes in EGFR-mutant lung cancer." (PMID 40701249, 2025). "Despite the promising findings of the current study, several limitations need to be addressed to optimize the therapeutic strategy for overcoming EGFR-TKI resistance in lung cancer." (PMID 39744423, 2025). "Recent reports indicate that CDK8 inhibition enhances the anti-cancer effects of MEK inhibitors, and in EGFR mutant lung cancer, the combination of EGFR inhibitors with YAP/TEAD inhibitors has shown synergistic effects." (PMID 40833497, 2025). "Although TLS expression has been shown to be prognostic for the efficacy of immune checkpoint inhibitors (ICIs), evidence in EGFR-mutant lung cancer remains limited." (PMID 40723259, 2025). "By suppressing cFLIP, these TKIs were believed to activate the extrinsic pathway of cell death in EGFR-mutant lung cancer cells." (PMID 40940888, 2025). "Targeted therapy is an important method in the treatment of lung cancer, especially in the detection of common NSCLC mutations such as epidermal growth factor receptor (EGFR), rat sarcoma viral oncogene (KRAS), anaplastic lymphoma kinase (ALK), and BRAF genes." (PMID 39962757, 2025). "Despite the significant improvement in survival with epidermal growth factor receptor (EGFR)‐tyrosine kinase inhibitors (TKIs), most patients with EGFR‐mutant non‐small cell lung cancer (NSCLC) develop EGFR‐TKI resistance." (PMID 40843133, 2025). "In vitro as well as in vivo studies confirmed that YAP1/WWTR1/TEAD-dependent transcription is acutely activated after osimertinib treatment in EGFR-mutant lung cancer, and pharmacological and genetic ablation of this complex strongly inhibits persister cells." (PMID 40428391, 2025). "Although the development and use of EGFR-TKIs have improved the management of lung cancer in the clinic, toxicity of these agents and development of resistance are of concern." (PMID 40940888, 2025). "Targeted therapies with epidermal growth factor receptor (EGFR) tyrosine kinase inhibitors (TKIs) represent a significant advance in the management of lung cancer." (PMID 41154639, 2025). "Single-cell RNA sequencing studies of EGFR-mutant lung cancer have revealed that DTP cells display distinct gene expression profiles compared to the parental tumor cells." (PMID 40003951, 2025). "EGFR-TKIs (e.g., gefitinib, osimertinib) combined with pan-HDAC inhibitors (e.g., trichostatin A, vorinostat) enhance growth inhibition and synergistically reduce the viability of EGFR-mutant lung cancer cells through apoptosis." (PMID 40290805, 2025). "Previous literature demonstrated that combined inhibition of MEK and EGFR prevents the emergence of resistance in EGFR-mutant lung cancer." (PMID 40568132, 2025).
lung cancer (continued). "Activation of epidermal growth factor receptor (EGFR) or anaplastic-lymphoma-kinase (ALK) is particularly important for lung cancer cells to survive and outgrowth in brain." (PMID 39998776, 2025). "The most common target for tyrosine kinase inhibitor therapy in lung cancer is Epidermal Growth Factor Receptor (EGFR)." (PMID 41516258, 2025). "In this review, we highlight the critical role of single-cell RNA sequencing in lung cancer research, with a particular focus on its application to exploring the mechanisms of EGFR-TKI-acquired resistance in NSCLC." (PMID 40003951, 2025). "In EGFR-mutant lung cancer, AXL, a receptor tyrosine kinase, plays a pivotal role in mechanisms of resistance to targeted therapy." (PMID 40003951, 2025). "In this study, neuroendocrine-transformed EGFR-mutant lung cancer exhibited variable DLL3 expression." (PMID 41256964, 2025). "Epidermal growth factor receptor tyrosine kinase inhibitors (EGFR-TKIs) have a significant curative effect on EGFR-mutant lung cancer; however, patients treated with EGFR-TKIs eventually experience disease progression due to acquired drug resistance." (PMID 40713600, 2025). "Epidermal growth factor receptor (EGFR)-mutant tumors have become key targets in the study of lung cancer resistance since their discovery in 2004." (PMID 40304000, 2025). "Conventional chemotherapy (taxanes, platinum-based agents), EGFR-tyrosine kinase inhibitors (TKIs), and ICIs have improved outcomes in breast and lung cancer but remain constrained by toxicities, acquired resistance, and immune-related adverse events (irAEs)." (PMID 41228309, 2025). "In a study of patients with EGFR-mutant lung cancer who developed acquired resistance to erlotinib or gefitinib, rapid disease progression was observed after the discontinuation of these tyrosine kinase inhibitors (TKIs) during a clinical trial washout period." (PMID 40271285, 2025). "Erlotinib transcriptionally downregulates CIP2A to upregulate PP2A and is primarily used to treat EGFR-mutant lung cancer." (PMID 40487848, 2025). "In EGFR TKI‐resistant lung cancer, inhibition of Aurora B kinase can inactivate the ATR–CHK1–Aurora B axis and induce apoptosis of EMT cells." (PMID 41415713, 2025). "This case highlights ivonescimab’s dual-mechanism potential to overcome resistance in EGFR-mutant Non–small cell lung cancer (NSCLC) by concurrently alleviating PD-1-mediated immunosuppression and VEGF-driven angiogenesis." (PMID 41383506, 2025). "In previous studies, the toxicity profiles of TKIs in lung cancer therapy have been extensively studied for EGFR and ALK inhibitors." (PMID 40949148, 2025). "Treatment with tyrosine kinase inhibitors (TKIs) osimertinib that targeting activated EGFR can prolong the survival of patients with EGFR mutant lung cancer." (PMID 39998776, 2025). "The synergistic effects of triptolide when used alongside other medications, such as EGFR inhibitors in lung cancer, TRAIL receptor agonists in renal cell carcinoma, and Bcl-2 inhibitors in leukemia, further highlight its therapeutic promise." (PMID 40490812, 2025). "Multivariate analysis of predictive factors for PFS in patients with non‐small cell lung cancers who received atezolizumab in combination with bevacizumab, carboplatin or cisplatin and pemetrexed after failure of EGFR tyrosine kinase inhibitors." (PMID 39715697, 2025). "This contrasts with work in other cancer types—such as gliomas and lung cancer—where radiogenomic models are increasingly deployed to infer EGFR or IDH status directly from imaging features." (PMID 40900793, 2025).
lung cancer (continued). "In order to investigate the relationship between tumor microenvironment and EGFR-TKI resistance in lung cancer, we tested the expression levels of tumor tissue markers in lung cancer patients with drug resistance." (PMID 40703348, 2025). "In relation to the precision of lung cancer diagnosis, a study demonstrated that ExoDx (EGFR) exhibits a sensitivity of 90% for L858R, 83% for T790M, and 73% for exon 19 indels, with corresponding specificities of 100%, 100%, and 96%, respectively." (PMID 41573685, 2025). "This should be followed by the selection of targeting ligands that are matched to biomarkers that are prevalent in specific lung cancer subtypes, such as the overexpressed CB2 receptor or EGFR variants." (PMID 41011117, 2025). "Datoptamab deruxtecan has recently received FDA approval for patients with EGFR mutant lung cancer following progression on standard therapies." (PMID 41438982, 2025). "For instance, AQP3-mediated H2O2 uptake was correlated with the activation of the EGFR signaling pathway in human squamous cell carcinoma and lung cancer cell lines, contributing to cancer progression." (PMID 39941100, 2025). "While the levels of exosomal EGFR is significantly increased in lung cancer patients, the concentration of soluble EGFR in plasma does not show a notable difference." (PMID 40575159, 2025). "Other BsAbs targeting different tumor antigens, such as HER2 and EGFR, are under investigation for their potential use in lung cancer." (PMID 40805219, 2025). "In lung cancer, EGFR-TKI resistance promotes immune escape in lung cancer via increased PD-L1 expression." (PMID 39192657, 2025). "In summary, targeted therapies in lung cancer exemplify the paradigm of drugging specific oncogenic drivers such as EGFR, ALK, and KRAS, thereby providing substantial clinical benefit for well-defined molecular subgroups." (PMID 41472727, 2025). "To address this, we investigated the contribution of APOBEC mutagenesis to acquired therapy resistance in a model of EGFR-mutant non–small cell lung cancer." (PMID 40323013, 2025). "The selection of a local intervention, such as surgery, and radiotherapy (including chemoradiotherapy), or EGFR-TKI prescription in patients with lung cancers harboring EGFRmt following postoperative recurrence remains under debate." (PMID 39842815, 2025). "We show the evolution of a case of EGFR mutant lung cancer treated with a combination of erlotinib, osimertinib, radiotherapy and a personalized neopeptide vaccine targeting somatic mutations, including EGFR exon 19 deletion." (PMID 39972134, 2025). "For instance, CD200‐positive CAFs significantly enhance the efficacy of the epidermal growth factor receptor (EGFR)‐tyrosine kinase inhibitor gefitinib against lung cancer cells." (PMID 41498024, 2025). "Overall, these results suggest that MEOX2 and GLI-1 play divergent roles in lung cancer progression, and response to EGFR-TKIs-based therapy, with both MEOX2/GLI-1 potentially influencing EGFR gene expression." (PMID 39971779, 2025). "Collectively, these data indicated that L-1 suppresses lung cancer cell growth in vitro and in vivo by targeting EGFR mutant." (PMID 39753983, 2025). "Generally, in our hospital, the time from the initial diagnosis of lung cancer to the EGFR test report spans about one to two weeks." (PMID 40310364, 2025). "ADCs are emerging as a promising class of therapeutics across a broad range of lung cancers, with the potential to overcome heterogenous resistance mechanisms of EGFR-mutant NSCLC after TKI progression." (PMID 41438982, 2025). "We tracked the phylogenetic history of an EGFR mutant lung cancer treated with erlotinib, osimertinib, radiotherapy and a personalized neopeptide vaccine (NPV) targeting ten somatic mutations, including EGFR exon 19 deletion (ex19del)." (PMID 39972134, 2025).
lung cancer (continued). "Further validation of EGFR expression revealed significantly elevated EGFR levels in lung cancer patients compared with healthy individuals." (PMID 41465428, 2025). "Recent studies have unveiled that lung cancer cells resistant to EGFR-TKIs exhibit characteristics indicative of a stemness phenotype." (PMID 39744423, 2025). "This phenomenon is especially notable in cancer varieties where there are potent targeted therapies for key growth pathways, such as AR‐driven prostate cancer, epidermal growth factor receptor (EGFR)‐mutant lung cancer, and BRAF‐mutant melanoma." (PMID 40013333, 2025). "Most lung cancer patients treated with first-generation EGFR-TKI develop resistance about 1 year after treatment." (PMID 40732366, 2025). "Given the substantial overlap, we focused our analysis on EGFR, representing the target protein with the most comprehensive set of common pathways related to lung cancer." (PMID 41155483, 2025). "Simultaneously, multiple lines of evidence from research suggested that lidocaine inhibited the progression of lung cancer, colorectal cancer and retinoblastoma via regulation of EGFR axis." (PMID 39888904, 2025). "EGFR is vital to lung cancers in pathogenesis and disease progression, and it is aberrantly expressed in NSCLC." (PMID 39859343, 2025). "CAFs have also been shown to promote resistance in lung cancer cells to epidermal growth factor receptor‐tyrosine kinase inhibitors (EGFR‐TKIs)." (PMID 40162549, 2025). "Since targeted therapy provides meaningful survival benefits and quality-of-life improvements in advanced lung cancer, accurate detection of EGFR status before treatment is crucial throughout clinical management." (PMID 41573643, 2025). "(C, D) Western blots (C) and RT-qPCR (D) analyses of indicated parental and EGFR inhibitor resistant lung cancer cells." (PMID 40243589, 2025). "While ICIs such as nivolumab, pembrolizumab (anti-PD-1), and atezolizumab (anti-PD-L1) are approved for EGFR wild-type lung cancer treatment, their effectiveness is limited by both intrinsic and acquired resistance." (PMID 40347254, 2025). "The high burden of lung cancer in developing countries has led to the widespread use of EGFR inhibitors like osimertinib." (PMID 41271435, 2025). "Presently, EGFR-TKI resistance in lung cancer arises through various mechanisms, including secondary mutations in EGFR (e.g., T790M), activation of alternative signaling pathways (e.g., MET, HER2), phenotypic transformation (small cell transformation)." (PMID 39744423, 2025). "EGFR is overexpressed in many tumor cells, such as glioma, renal cell carcinoma, lung cancer, prostate cancer, pancreatic cancer, and breast cancer cells." (PMID 39907159, 2025). "Further accumulation of such case reports is important to establish optimal treatment approaches for patients with EGFR L861R‐positive lung cancer." (PMID 41350121, 2025). "EGFR has been demonstrated to directly modulate fatty acid synthesis, thereby promoting lung cancer progression." (PMID 40872626, 2025). "In contrast, atypical EGFR variants, such as exon 20 insertions and less common point mutations (G719X, S768I, L861Q), often exhibit primary resistance to currently available TKIs, underscoring the biological heterogeneity of EGFR-driven lung cancer." (PMID 41438982, 2025).
lung cancer (continued). "In conclusion, this case offers two critical insights for managing EGFR-mutant lung cancer with MPE and complex resistance within the continuously changing treatment landscape." (PMID 41479892, 2025). "This supports previous research showing that lung cancer patients with lower MEOX2 expression and EGFR mutations had better overall survival with combined cisplatinum and TKI therapy." (PMID 39971779, 2025). "Our findings suggest that ΔNp63 contributes to TKI resistance in squamous transdifferentiated lung cancer cells as knockout of p63 sensitized these cells to third-generation EGFR inhibitors, like osimertinib." (PMID 40323013, 2025). "It was also reported that Bim upregulation and Mcl-1 suppression were needed for osimertinib to mediate its apoptotic effects in EGFR-mutant lung cancer cells." (PMID 40940888, 2025). "As but one example, drugs that inhibit oligosaccharyltransferase, the enzyme that transfers oligosaccharides to proteins to facilitate folding, have shown promise in non–small cell lung cancer by selectively blocking EGFR." (PMID 40789468, 2025). "Firstly, our study focused on populations and patient tissues, and PDX mice and lung cancer cells should be investigated in future studies to uncover EGFR SNPs." (PMID 40438325, 2025). "The mechanisms of lung cancer tumorigenesis are vastly complex, and the relationship between tumor growth and resistance to EGFR TKIs merits investigation." (PMID 40722726, 2025). "In this study, we performed a microarray screening and identified HDAC5, a class IIa HDAC, which was rapidly upregulated by osimertinib in EGFR-mutant lung cancer cells." (PMID 40290805, 2025). "Since EGFR became a promising therapeutic target, EGFR inhibitors have revolutionized the treatment paradigm in lung cancer." (PMID 39941723, 2025). "The most important finding of this study was the improved clinical outcome associated with CTNNB1 comutations when present at baseline in EGFR-driven lung cancer." (PMID 40768678, 2025). "In summary, our findings highlight caffeic acid as the most promising M. oleifera-derived compound with strong inhibitory potential against EGFR, a key driver of lung cancer progression." (PMID 41155483, 2025). "Although this remains to be fully investigated, the lung cancers with mutant EGFR tend to have fewer tumor-infiltrating lymphocytes (TILs), such as CD8+ T cells." (PMID 40940888, 2025). "From the protein–pathway interactions, the most prominent protein identified is EGFR, which regulates most of the lung cancer-enriched pathways." (PMID 41155483, 2025). "Lastly, we examined 20 human lung cancer patient‐derived xenografts (PDXs) for agrin, EGFR, and YAP expression." (PMID 40165020, 2025). "Another study reported that 73% of canine lung carcinomas were immunohistochemically positive for EGFR, using a minimum cutoff of 10% of tumor cells positive within the tissues evaluated." (PMID 40969344, 2025). "The NCI-H1650 lung carcinoma cell line harbours the EGFR exon 19 deletion (DelE746-A750) and is resistant to EGFR tyrosine kinase inhibitors." (PMID 41008840, 2025). "Anti-EGFR CAR-T therapy shows promise for treating EGFR-positive lung carcinoma, but additional clinical validation is necessary." (PMID 40922740, 2025). "Several biomarkers (such as EGFR, BRAF, KRAS gene mutations, etc.)have emerged as predictive and prognostic markers for lung cancer." (PMID 38730722, 2024). "Previous studies have shown that LLC/LL2 lung cancer cells exhibit a high expression level of EGFR in several cancer cell lines." (PMID 39273055, 2024). "Lung cancer, head and neck cancer and esophagus carcinoma have several commonalities in terms of EGFR with increased expression of EGFR, high frequency of EGFR amplification and low indel mutations." (PMID 39138146, 2024). "Drug sensitivity assay showed that GLI2 overexpression significantly (p < 0.01) enhanced drug resistance of lung cancer cells against targeted EGFR inhibitors and conventional chemotherapy drugs." (PMID 37950038, 2024).